ASPH (aspartate beta-hydroxylase)
Diseases named in the same sentence as ASPH in open-access papers (continued):
Sharing a sentence is not in itself a finding about the gene and the disease.
tumor (continued). "Overexpression of ASPH has been reported in more than 20 tumor types." (PMID 34996491, 2022). "In addition, PD-L1 expression was upregulated on tumor cells by signaling through ASPH-Notch-MYC in both murine TNBC and HCC animal models." (PMID 35392977, 2022). "Furthermore, it is reported recently that the angiogenic effects of tumour EVs are mainly mediated by aspartate β‐hydroxylase (ASPH) signalling." (PMID 33586248, 2021). "ASPH can be used not only as a target of the inhibitors inactivating its enzymatic activity but also as a target of immune reactions leading to destruction of tumor cells and tumor growth suppression." (PMID 32811566, 2020). "In 7801 tumor tissues, ASPH also showed a positive correlation with RUNX2 as well as COL1A1." (PMID 33015050, 2020). "The observation that increased levels of AspH on the surface of cancer cells correlates with enhanced tumour invasiveness coupled with the observations that AspH is upregulated in many tumours and is hypoxically regulated, renders AspH an interesting potential cancer target." (PMID 32457455, 2020). "As potential targets of ASPH hydroxylation are also expressed on immune cells, this enzyme could affect the function of immune system, particularly in tumor microenvironment when ASPH is overexpressed on cancer cells." (PMID 32811566, 2020). "ASPH also promotes tumor growth by stimulation of angiogenesis and immunosuppression." (PMID 32811566, 2020). "Tumor growth and invasiveness could further be supported by ASPH-induced extracellular matrix degradation, angiogenesis, and transendothelial migration." (PMID 32811566, 2020). "AspH is upregulated in several cancer-types and is reported to be translocated from the endoplasmic reticulum (ER) membrane to the cell surface, a process which is reported to correlate with enhanced tumour invasiveness and poor prognosis." (PMID 32457455, 2020). "The ASPH-SRC axis guides tumor cells to strengthen invadopodia formation/maturation and ECM degradation/remodeling, migration, invasion, stemness, transendothelial migration (intravasation/extravasation), and metastatic colonization/outgrowth at distant sites (e.g., lungs)." (PMID 31888763, 2019). "The structures reported here may also of be interest with respect to defining factors involved in AspH localisation, in particular to the surfaces of some tumour cells." (PMID 31659163, 2019). "This hypothesis raises the possibility that targeting ASPH to reduce its level or activity may suppress tumor growth and inhibit cellular migration and invasion." (PMID 26954680, 2016). "ASPH upregulation confers a malignant phenotype characterized by enhanced cell proliferation, migration, invasion and colony formation in vitro as well as PC tumor growth in vivo." (PMID 25483102, 2015). "Therefore, the expression of ASPH is related to tumor resistance to chemotherapy." (PMID 40110547, 2025). "Thus, the inhibitors of ASPH could be affecting the tumors by acting on both the tumor cells and on the CAF." (PMID 38732216, 2024). "Furthermore, the knockout of ASPH could significantly reduce the proliferation of tumor cells in vitro and lessen tumorigenicity in vivo, which are compatible with previous reports." (PMID 36982561, 2023). "Mechanistically, anti-CE1 antibodies cross-react with aspartate β-hydroxylase (ASPH), with CE1-ASPH sequence homology underpinning tumor recognition and cytotoxicity." (PMID 41993253, 2026). "First, while our in vitro assays provide initial functional support, the study lacks in vivo validation using animal models, which is essential to confirm the roles of ASPH and PTTG1 in a physiological tumor microenvironment." (PMID 41312363, 2025). "Western blot analysis revealed that the protein expression levels of ASPH and PTTG1 were significantly higher in tumor tissues compared to adjacent normal tissues across all six paired LUAD samples (P < 0.001)." (PMID 41312363, 2025).
tumor (continued). "The use of databases, such as GENT2 and HPA, facilitated the further identification of ALDH18A1 and ASPH as critical SASP factors with unfavorable prognostic outcomes, highlighting their tumor-promoting potential." (PMID 39858632, 2025). "This study is the first to validate, at the protein level, the significant overexpression of ASPH and PTTG1 in LUAD tumor tissues, which is consistent with previous findings based on single-cell transcriptomics and bioinformatic analyses." (PMID 41312363, 2025). "Expression of ASPH is positive with log2 (IC50) of paclitaxel (p=7.6e-6, r=0.16), and the log2 (IC50) of paclitaxel is higher in high expression ASPH tumor cells (p=1.4e-4)." (PMID 40110547, 2025). "On the contrary, a statistically significantly higher number of cells producing ASPH (p < 0.0001), HIF1A (p < 0.0001), GLUT1 (p < 0.0001), and MMP13 (p < 0.05) proteins were detected in the HPV-positive tumor group than in the HPV-negative sample group." (PMID 38858774, 2024). "To extend our findings to human cells, we tested the levels of Ly6D and Ly6K proteins, which are upregulated in various tumor types 53, in 5 human tumor cell lines (HeLa, SiHa, CaSki, Detroit 562, and MCF-7) and showed their reduction after ASPH inhibition." (PMID 38356711, 2024). "ASPH upregulation activates the Notch, MAPK and PI3K signaling pathways, delays tumor cell senescence, destroys the integrity of mitochondria, and subsequently leads to tumor development." (PMID 36765881, 2023). "The downregulated expression of ASPH can repress EMT signaling pathways in GC cells and restrict tumor growth." (PMID 36982561, 2023). "We identify PYGL, ASPH and CD45 as spatial markers for tumour boundary and reveal immune response-driven, spatially-organised protein networks of the extracellular tumour matrix." (PMID 38001067, 2023). "Synergistic antitumor efficacy attributable to a λ phage vaccine specifically targeting ASPH, an ideal TAA, combined with ICIs, inhibits tumor growth and progression of TNBC and HCC." (PMID 35392977, 2022). "In summary, ASPH is overexpressed in approximately 40% of AML cases, and can serve as a potential immunotherapeutically targetable tumor-specific antigen." (PMID 35004304, 2021). "Intriguingly, the analysis showed that ASPH has considerable positive correlations in mRNA expression with GSK3B and CTNNB1 in most of normal/tumor tissues." (PMID 33015050, 2020). "However, how the biochemistry of AspH affects tumour cell motility is unknown." (PMID 32457455, 2020). "Since the only difference between these two cell lines was the presence or absence of exogenous ASPH expression, PC tumor development and growth may be most susceptible to a SMI of β-hydroxylase activity in those tumors that have high levels of ASPH expression." (PMID 25483102, 2015). "Here, treating TC-1/A9-induced tumors with the ASPH inhibitor MO-I-1151 alone or in combination with the ODN1826 adjuvant did not significantly reduce tumor growth." (PMID 40655119, 2025). "Surprisingly, ASPH inhibition did not further support tumor growth inhibition induced by the potent combination of DNA vaccination and ODN1826 administration." (PMID 40655119, 2025). "ASPH inhibition did not reduce tumor growth or promote the anti-tumor effect of innate immunity stimulation with the synthetic oligonucleotide ODN1826, but it significantly enhanced tumor growth reduction induced by DNA vaccination." (PMID 40655119, 2025). "High expression of ASPH significantly enhances the VISFATIN signaling pathway among epithelial, fibroblast, myeloid cell and macrophage and SPP1 signaling pathway among epithelial, fibroblast and macrophage in the tumor microenvironment of gallbladder." (PMID 40110547, 2025). "While treatment with ODN1826 alone or in combination with an ASPH inhibitor did not reduce tumor growth, DNA vaccination showed a modest anti-tumor effect." (PMID 40655119, 2025).
tumor (continued). "Genes involved in glycolysis (ALDOA, LDHA, PGK1, PFKL, PGM1) and other metabolic processes (GPX4, PRDX4, ACO2, ASPH, IDH2, SQLE, NPC2, SPTSSA) were upregulated in primary tumor cells, suggesting that the metabolism in primary tumors was distinct from that in their matched metastasis." (PMID 39225101, 2024). "In pancreatic cancer, ASPH has also been reported to interact with ADAM 12/15, thus activating SRC kinase pathway proteins that control MMP-mediated extracellular matrix degradation and tumor invasion." (PMID 38732216, 2024). "Expression of ASPH is aberrantly increased in PDAC and also other cancers such as hepatocellular carcinoma and prostate cancer, and has been reported to contribute to proliferation, migration, invasion, recurrence, and tumor invasiveness 9,89,90." (PMID 34522225, 2021). "Genes ASPH, HSPB1, SQSTM1, ANXA2, and GSN (Cluster A) and PURA and MX1 (Cluster B) were downregulated for both datasets in PCa tissue vs. normal gland or normal adjacent to tumor tissue." (PMID 32640729, 2020). "Overexpressed ASPH directly interacts with ADAM12/15 and strengthens the SRC activation by these proteins which promotes MMP-mediated extracellular matrix degradation and tumor invasiveness." (PMID 32811566, 2020). "Targeting ASPH may suppress CSC generation and promote apoptosis, which is another key event to control tumor cell proliferation and progression." (PMID 26954680, 2016). "Moreover, ASPH and PTTG1 may themselves play regulatory roles in drug response pathways, thereby influencing tumor cell sensitivity to specific treatments." (PMID 41312363, 2025). "ASPH was uniformly high in expression, irrespective of tumor stage." (PMID 38732216, 2024). "The elevated expression of ASPH on the surface of HCC tumor cells but not cells in surrounding, noninvolved tissues suggests that ASPH could serve as an immunotherapeutic target." (PMID 36293298, 2022). "Since most studies have shown that ASPH is overexpressed in malignant tumor cells and low or no expression in normal tissues and overexpressed ASPH can be detected by releasing from tumor cells into human serum and body fluids, ASPH can be used as a novel tumor marker and therapeutic target." (PMID 35965520, 2022). "Although the exact tumor-promoting mechanisms of ASPH have not been elucidated yet, it has been hypothesized that this protein might be involved in several tumorigenic pathways, including the Notch pathway." (PMID 34522225, 2021). "Moreover, as antigenic epitopes that reside on the ASPH protein can efficiently stimulate cluster of differentiation (CD) 4+ and CD8+ T-cell responses unique to tumor cells harboring ASPH, this enzyme can be used as a tumor associated antigen (TAA) in immunotherapy." (PMID 32811566, 2020). "ASPH expression does not differ significantly between the tumor epithelium and stroma either in intensity or in distribution, which shows that CAF and other non-cancer cells are an important source of ASPH." (PMID 38732216, 2024). "However, as a critical paralog of ASPH, the relationship between ASPHD1 and cancer is less studied, and its role in the occurrence and progression of neoplasm is not clear." (PMID 37004045, 2023).
cancer (50 papers, 2006 to 2026). A tumor composed of atypical neoplastic, often pleomorphic cells that invade other tissues. "ASPH is upregulated in several malignant neoplasms where it propagates a malignant phenotype associated with increased cell proliferation, invasiveness, and metastasis, and with poor clinical prognosis 9,10,16,18." (PMID 38356711, 2024). "Single-cell transcriptomic analysis of HNSCC shows that ASPH is expressed in cancer cells but also in the cancer-associated fibroblasts (CAFs) and endothelial cells." (PMID 38732216, 2024). "Human aspartate β-hydroxylase (ASPH) is associated with various types of cancer, and it has been well-tolerated in vaccines, inducing an immune response." (PMID 36851313, 2023). "Aspartate β-hydroxylase (ASPH) is an embryonic transmembrane protein aberrantly upregulated in cancer cells, associated with malignant transformation and, in some reports, with poor clinical prognosis." (PMID 35004304, 2021). "Surprisingly, we found ASPH was associated with cellular senescence in cancer and possibly involved in bone health." (PMID 33015050, 2020). "Despite an undefined biochemical role for ASPH-catalyzed hydroxylation, mutations in ASPH are associated with severe facial abnormalities, and ASPH overexpression is linked to malignant transformation and poor prognosis in human cancers." (PMID 26152730, 2015). "ASPH has been identified as one of the genes which upregulated expression could serve for risk stratification of patients with 9 cancer types." (PMID 32811566, 2020). "The results reveal how AspH accommodates both aspartate- and asparagine-substrates and will assist in efforts targeting AspH for cancer treatment." (PMID 41741441, 2026). "ASPH is expressed by cancer cells; thus, the fluorescence signal was observed in both untreated cancer cell lines." (PMID 39980072, 2025). "This study introduces new challenges and opportunities in the development of ASPH inhibitors and their potential application in cancer treatment, but some questions remain unanswered." (PMID 40655119, 2025). "We evaluate key factors related to cancer cell viability, energy metabolism, and calcium homeostasis, including ATP levels, ROS generation, and ASPH expression." (PMID 39980072, 2025). "Small-molecule AspH inhibitors have shown potential in both cellular and animal studies to suppress cancer progression related to AspH upregulation; however, the long-term safety of these inhibitors has not yet been investigated." (PMID 41354343, 2025). "ASPH is widely expressed in cancer cells and responsible for cancer proliferation, migration, and invasion." (PMID 39980072, 2025). "ASPH also promotes epithelial-to-mesenchymal transition, angiogenesis, and immune evasion, all of which are critical for cancer progression." (PMID 39858632, 2025). "Since increased expression of Ly6 genes is associated with progression of both mouse and human tumors, their upregulation with ASPH can enhance the effect of ASPH in tumorigenesis and strengthen its role as a target in cancer therapy." (PMID 38356711, 2024). "ASPH is upregulated in various malignant neoplasms; it has been detected in 70-90% of human solid tumors, where it plays a crucial role in mediating a malignant phenotype characterized by increased cell proliferation, invasion, and metastasis 5-8." (PMID 38817852, 2024). "Targeting ASPH with inhibitor MO-I-1151 effectively reduces CAF-mediated cellular invasion in cancer cell models." (PMID 38732216, 2024). "This study highlights the complex nature of ASPH-mediated regulation, involving not only the Notch1 pathway but also diverse pathways in different cancer types, and emphasizes the importance of targeting multiple pathways to reduce cancer progression." (PMID 38817852, 2024). "This is a first report of the effect of MO-I-1151 on inhibiting ASPH in HNSCC cancer cells and arresting cellular migration and invasion." (PMID 38732216, 2024).
cancer (continued). "This investigation focused on less studied cell lines in the context of ASPH-mediated tumorigenesis to provide novel insights into the impact of ASPH inhibitors in a broader spectrum of cancer scenarios." (PMID 38817852, 2024). "ASPH is upregulated in various cancer types, where it promotes cancer progression mainly by regulating the Notch1 and SRC pathways." (PMID 38817852, 2024). "In this study, we investigated the intricate interaction between ASPH and the Notch1 signaling pathway in various cancer cell lines." (PMID 38817852, 2024). "Accumulating evidence has demonstrated that ASPH plays a significant role in the tumorigenic transformation of cancer cells by enhancing proliferation, differentiation, motility and anti-apoptosis ability." (PMID 36982561, 2023). "The staining intensity of ASPH expression in cancer tissues undergoing NACT displayed an obvious increase in comparison to that in those without NACT (positive staining: 76.5% with NACT vs. 59.3% without NACT)." (PMID 36982561, 2023). "Labyrinthin has sequence homology with members of the ASPH gene family but is distinct with respect to having a role as both a cancer marker and target." (PMID 37415228, 2023). "ASPH has also been identified as a marker in various cancers, and likely alters Calcium homeostasis." (PMID 36785619, 2023). "Together, these results demonstrate that the effect of the knockout of ASPH on cancer cells was amplified when exposed to chemotherapeutic agents." (PMID 36982561, 2023). "The type II transmembrane protein aspartate β-hydroxylase (ASPH) is overexpressed in different cancer types and involved in proliferation, invasion, and metastasis." (PMID 37048115, 2023). "This system can provide personalized cancer therapy depending on unique and functional targets, such as ASPH." (PMID 35392977, 2022). "Aspartyl/asparaginyl β-hydroxylase (ASPH), a promising therapeutic target, is overexpressed in a variety of malignant tumors but is expressed negligibly in normal tissues." (PMID 36293298, 2022). "By informing on the cellular substrates of AspH, we hope that the results presented here will help enable the development of potent and selective small-molecule inhibitors of AspH, which is of interest from a cancer treatment perspective." (PMID 35700824, 2022). "Meanwhile, NLSs deletion led to cytoplasmic localization of INPP5F, providing an opportunity to bind to ASPH and thereby activate the Notch pathway to exert its cancer-promoting function." (PMID 34996491, 2022). "Recent studies have pointed out the crucial regulatory role of ASPH in the initiation and development of cancers." (PMID 33526034, 2021). "We report widespread and consistent changes in alternative splicing of cancer-associated genes including CENPE, ESCO2, CKAP2, MELK, ASPH and CD164 in both HeLa and PC3 cells." (PMID 33846420, 2021). "AspH is reported to be upregulated on the cell surface of invasive cancer cells in a manner distinguishing healthy from cancer cells." (PMID 33069066, 2020). "We report studies on the effect of small-molecule active pharmaceutical ingredients (APIs) of human cancer therapeutics on the catalytic activity of AspH using a high-throughput mass spectrometry (MS)-based inhibition assay." (PMID 33069066, 2020). "AspH is present on the cell surface of invasive cancer cells and accepts epidermal growth factor‐like domain (EGFD) substrates with a noncanonical (i. e., Cys 1–2, 3–4, 5–6) disulfide pattern." (PMID 32330361, 2020). "ASPH is upregulated in several malignant neoplasms (hepatocellular, pancreatic, lung and neural carcinomas) and correlates with a reduced survival rate." (PMID 32295249, 2020). "Considering that quercetin uptake has been correlated to inhibit cancer progression, it is possible that the inhibition of AspH accounts for some of its biological effect, however, it should be noted that the effects of flavonoids are likely pleiotropic." (PMID 32457455, 2020).